AKT2 (AKT serine/threonine kinase 2)
Diseases named in the same sentence as AKT2 in open-access papers (continued):
Sharing a sentence is not in itself a finding about the gene and the disease.
breast tumor (13 papers, 2008 to 2025). "Specifically, we analyzed Akt1 and Akt2, the two isoforms most closely related to invasiveness in breast tumors and that we found modified by garlic extract in other breast tumor cells." (PMID 41228363, 2025). "The TNBC cell lines under investigation were then treated with garlic extract and first subjected to immunochemical analysis of the expression and activation status of Akt1 and Akt2, the most studied isozymes in breast tumors." (PMID 38786044, 2024). "The data reported here demonstrated a peculiar role of the multidomain protein Vav1 in breast tumor cells with a triple negative phenotype, consisting in down-modulation of the oncogenic protein Akt2 through the up-modulation of the tumor suppressor miR-29b." (PMID 35743776, 2022). "In the same breast tumor, it was recently demonstrated that miR-29b down-regulates cells growth in 3D cultures by abrogating the expression of different oncogenes including Akt2." (PMID 35743776, 2022). "We further explored the possible role of Vav1 in modulating Akt2, whose expression is phenotype‐dependent and whose role in breast tumors seems to be different from that of Akt1 and mainly associated with migration and metastasis." (PMID 29658179, 2018). "Although both AKT1 and AKT2 are required for breast tumor growth, AKT1 appears to suppress, while AKT2 promotes tumor metastasis." (PMID 26895380, 2016). "As a major downstream effector of PI3K/AKT survival pathway, AKT2 expression markedly increased the incidence of pulmonary metastases in breast tumor model." (PMID 25288334, 2014). "We confirmed that Akt1 and Akt2 are widely expressed in HER2-positive breast tumours and, simultaneously, tumours contain their activated form." (PMID 22842582, 2012). "Our further investigations have been therefore oriented to establish whether, in breast tumor as in leukemic cells, Vav1 can modulate the expression of miRNA/s, in turn responsible for targeting Akt2." (PMID 35743776, 2022). "It is now known that PIK3CA is mutationally activated in up to 40% of ER alpha-positive tumors; PTEN levels are decreased in a similar proportion, and AKT2 (up to 5%) and p70S6K (10-20%) may also be overexpressed by amplification in some breast tumors." (PMID 33299611, 2020). "This may contribute to the distinct ability of Akt1 to promote breast tumor initiation and impair invasion and migration, while Akt2 enhances the invasive and metastatic capabilities of breast tumors." (PMID 31131274, 2019). "A recent study also showed that AKT2 but not AKT1 is required for the maintenance of PTEN-deficient breast tumor spheroids in 3D culture." (PMID 26895380, 2016). "Akt2 frequently has been found to be upregulated in HER2/neu-positive breast tumors and may contribute to tumor aggressiveness and metastases." (PMID 18184439, 2008). "The evidence that none of the mice receiving cells over-expressing Vav1 developed lung aggregates of breast tumor cells suggests a protective role of the Vav1-induced miR-29b against the facilitation of extravasation of tumor cells into lung parenchyma, which was proposed to correlate with Akt2." (PMID 35743776, 2022). "High BRCA1-IRIS expression was detected in the majority of human breast tumors analyzed, which was positively correlated with that of AKT1-, AKT2-, p-AKT-, survivin, but negatively with BRCA1/p220 expression." (PMID 22511931, 2012). "Immunohistochemical staining of large cohort of human breast tumor samples using new monoclonal anti-BRCA1-IRIS antibody, followed by correlation of BRCA1-IRIS expression with that of AKT1, AKT2, p-AKT, survivin and BRCA1/p220, tumor status and age at diagnosis." (PMID 22511931, 2012). "Overall, our data indicate that, in breast tumor‐derived cells with different phenotypes, the sole modulation of Vav1 is sufficient to affect the activation status of Akt1, involved in the insurgence and growth of breast tumors, but not of Akt2, mainly responsible of tumor metastasis." (PMID 29658179, 2018).
breast tumor (continued). "Therefore, the activated pAkt in breast tumors in our patient cohort determined by IHC may not be limited to phosphorylation of Akt1 or Akt2 only." (PMID 18184439, 2008).
Hypoglycemia (13 papers, 2011 to 2023). A decreased concentration of glucose in the blood. "Conversely, the same de novo activating mutation in the akt2 gene was carried by three unrelated patients with severe fasting hypoglycemia and asymmetric overgrowth (increased truncal adipose tissue)." (PMID 34639094, 2021). "In our cases, we decided to give sirolimus to improve hypoglycemia in a patient with AKT2 mutation and another patient with PTHS as sirolimus will inhibit mTOR, the next downstream step in PTEN/AKT signalling." (PMID 32157856, 2020). "The causes of hypoglycemia in AKT2 mutation are related to the activation of the insulin signalling pathway." (PMID 32157856, 2020). "On the other hand, patients carrying the activating mutation AKT2 E17K develop hypoglycemia, hypoinsulinemia, and increased body fat, which are clinical parameters similar to those in patients who have type I diabetes." (PMID 31835296, 2019). "The p.Glu17Lys mutation of AKT2 confers low-level constitutive activity upon the kinase and produces hypoglycemia with suppressed fatty acid release from adipose tissue, but not fatty liver, hypertriglyceridemia, or elevated hepatic de novo lipogenesis." (PMID 28541532, 2017). "The activating p.Glu17Lys mutation in AKT2, a kinase mediating many of insulin’s metabolic actions, causes hypoinsulinemic hypoglycemia and left-sided hemihypertrophy." (PMID 28541532, 2017). "More recently, E17K mutation in AKT1 has been associated with Proteus syndrome and a similar mutation in AKT2 was found in patients with rare hypoglycemia." (PMID 24978597, 2014). "Once the human safety profile has been well established, it will be tempting to explore them in patients with Proteus syndrome and/or hypoglycemia caused by AKT1 or AKT2 mutation, respectively." (PMID 24978597, 2014). "Sirolimus treatment, through mTOR inhibition, appeared to be effectively controlling the peristent hypoglycemia and may be a life-saving therapy in this NkHH due to AKT2 and PTEN mutations." (PMID 32157856, 2020). "A gain-of-function missense mutation in AKT2, Glu17Lys (E17K), is the cause of a hypoinsulinemic hypoketotic hypoglycemia, which is also a rare genetic disease in which there is constitutive expression of AKT2, leading to severe hypoglycemia, hypoinsulinemia, and increased body fat." (PMID 31835296, 2019). "Interestingly, patients with the AKT2 E17K mutation have hypoglycemia, which is also a symptom of type I diabetes." (PMID 31835296, 2019). "This case showed that patients with bi-allelic PTEN mutations can present with other PI3K-AKT-mTOR pathway-related features, including the recurrent respiratory infections observed in patients with PIK3CD mutations and hypoglycaemia observed in patients with AKT2 or AKT3 mutations." (PMID 29296277, 2017). "If liver-autonomous failure to derepress glycogenolysis/gluconeogenesis were the major abnormality explaining PROS-related hypoglycaemia, then only a small glucose requirement to maintain euglycaemia would be expected, as reported for patients with activating AKT2 mutations." (PMID 28566443, 2017). "Differences in the GH signaling pathway involving AKT2 can cause hypoglycemia, seizures and death." (PMID 22145038, 2011). "Aninsulinemic hypoglycemia due to genetic activation of AKT2 is a rare entity, described to date in only five patients." (PMID 28541532, 2017). "Nevertheless, despite this body of evidence linking AKT2 p.Glu17Lys to hypoketotic hypoglycemia, key questions remain about the pathogenesis and natural history of the syndrome." (PMID 28541532, 2017). "For example, a hyperactive mutation of AKT2, the gene required for insulin-induced translocation of GLUT4 to the plasma membrane, caused hypoinsunlinemic hypoglycemia in four patients." (PMID 27293546, 2016). "In cases with PTEN or AKT2 mutation, there is no effective therapy other than frequent feeding to counter hypoglycemia." (PMID 32157856, 2020).
Hypoglycemia (continued). "Two obese 17-year-old patients with genetic activation of AKT2 showed no fatty liver nor metabolic dyslipidemia, with persisting hypoglycemia and free fatty acid suppression in one." (PMID 28541532, 2017). "Fasting free fatty acid levels in the PROS cohort were not studied; however, in two patients with genetic AKT2 activation, we observed correlation of free fatty acid suppression with fasting hypoglycaemia." (PMID 28566443, 2017). "Our findings suggest that hypoglycemia driven by the AKT2 p.Glu17Lys mutant may not be lifelong and may remit under some circumstances, although whether developmental, genetic, or environmental modifying factors are most critical in this remains to be determined." (PMID 28541532, 2017).
Anxiety (10 papers, 2013 to 2023). Intense feelings of nervousness, tension, or panic often arise in response to interpersonal stresses. "Together these OFA and EPM data demonstrate that Akt1 and Akt2 deficiency affect the expression of anxiety-related behaviors in a sex-specific fashion." (PMID 33325370, 2020). "On the other hand, Akt1 and Akt3 have been identified as possible susceptibility genes for schizophrenia and Akt2 has been associated with anxiety- and depression-like behaviors." (PMID 31871542, 2019). "AKT2 deletion has also been associated with anxiety- and depression-like behaviors." (PMID 30781836, 2019). "Lately, Akt2 deletion has been associated with anxiety and depressive-like behaviors." (PMID 28442992, 2017). "Accordingly, Leibrock and collaborators (2013) found that Akt2 knockout (Akt2 −/−) mice, besides showing cognitive impairment, displayed an anxiety- and depressive-like phenotype." (PMID 37998350, 2023). "It has been shown that Akt2 knockout and heterozygote mice exhibit anxiety-like behavior and impaired hippocampal-dependent learning, emphasizing the role of Akt and its downstream targets in these processes." (PMID 35656538, 2022). "Like AKT1, AKT2 affects anxiety-like behavior in a sex-specific fashion and impacts contextual memory." (PMID 33325370, 2020). "We also demonstrate that Akt2 is required for the display of normal anxiety-like behavior and contextual fear memory." (PMID 33325370, 2020). "Male and female mice with single-isoform deletions of Akt1, Akt2, or Akt3 were assessed for anxiety-related behaviors in the open field arena (OFA) and elevated plus maze (EPM) tests." (PMID 33325370, 2020). "These cognitive deficits are interesting to note since the mutations related to the PDK1 and Akt signaling pathway, such as those in Akt2 knockout mice, presented a higher anxiety-like and depressive-like behavior, but were cognitively intact." (PMID 32457586, 2020). "In contrast, preliminary analyses show that Akt2 deletion produces selective anxiety and depression-like phenotypes in mice, thus suggesting that the Akt genes play differential roles in brain development and function." (PMID 28467426, 2017). "For instance, while Pdyn is the only gene positively correlated with anxiety-like behavior in XX mice, Htr1a, Cdk5, Adcy2, Akt1, Akt2, and Akt3 positively correlate with anxiety-like behavior in XY- mice." (PMID 24199867, 2013). "The reduced general activity of PDK1 exhibited by the hypomorphic PDK1 mice (PDK1hm) results in several behavioral differences related to anxiety and exploration assessed in various tests, while cognitively unimpaired Akt2 knockout mice (Akt2−/−) presented an anxiety- and depressive-like phenotype." (PMID 32457586, 2020). "In addition, signs of anxiety and depressive-like behaviors have been reported in AKT2 KO mice." (PMID 30781836, 2019). "In animal studies, mice lacking Akt2, an isoform of Akt, exhibited anxiety-like and depression-like behaviors." (PMID 31275123, 2019). "Recently, signs of anxiety and depressive-like behaviors have been reported in mice lacking Akt2." (PMID 28442992, 2017).
Glucose intolerance (10 papers, 2011 to 2024). Glucose intolerance (GI) can be defined as dysglycemia that comprises both prediabetes and diabetes. "Gene-enrichment pathways were involved in glucose intolerance, transcriptional mis-regulation in cancer, IR signaling (AKT2, RSK/RAS/MAPK), and lipid metabolism." (PMID 36782224, 2023). "Female offspring in the same model also have glucose intolerance; however, they exhibit increased GLUT4 protein expression and intracellular mRNA expression of Akt2, indicating attempts of positive adaptations to glucose intolerance." (PMID 31968625, 2020). "Other models of Akt suppression in the liver (i.e., deletion of hepatic insulin receptor or Akt2) also result in a reduction in TG accumulation along with glucose intolerance similar to that of the Tsc1−/− mice." (PMID 21479224, 2011).
lung adenocarcinoma (10 papers, 2014 to 2023). A carcinoma that arises from the lung and is characterized by the presence of malignant glandular epithelial cells. "Herein, our study mainly explored the function of AKT2 during cancer progression and uncovered a new post-transcriptional mechanism of AKT2 expression in lung adenocarcinoma (LUAD)." (PMID 32873299, 2020). "HSDL2 functions as an oncogene to promote the growth and metastasis of lung adenocarcinoma via promoting the expression of AKT2." (PMID 32211805, 2020). "Accordingly, it has been reported that suppression of Akt2 expression in human lung adenocarcinoma cell line A549 resulted in a notable inhibition of cellular invasion." (PMID 26234648, 2015). "It has been reported that suppression of Akt2 expression in human lung adenocarcinoma cell line A549 resulted in notable inhibition of cell proliferation and colony growth." (PMID 26234648, 2015). "Another report pointed out that microRNA-608 could inhibit human lung adenocarcinoma via the regulation of AKT2." (PMID 31621555, 2020). "We hypothesized that the suppression effect of siHSDL2 on the progression of lung adenocarcinoma depends on the AKT2 expression level." (PMID 32211805, 2020). "For instance, in lung adenocarcinoma, miR-520c-3p have a lower expression level and regulates its targets AKT1 and AKT2 expression." (PMID 36528556, 2022). "Shi’s researches suggested that HSDL2 was upregulated in the lung adenocarcinoma tissue and HSDL2 knockdown inhibited lung adenocarcinoma progression via downregulating AKT2 expression." (PMID 35948893, 2022). "We identified several targetable pathways in EGFR/KRAS/ALK-negative lung adenocarcinoma including PI3K/mTOR signaling (TSC1, PIK3CA, AKT2), receptor tyrosine kinase signaling (ERBB4), cell cycle regulation (CHEK2, CDC27), and DNA repair (PARP4)." (PMID 24576404, 2014). "Our results showed that AKT2, BIRC3, and ERK are potential targets of HSDL2 in lung adenocarcinoma." (PMID 32211805, 2020).
leukemia (9 papers, 2019 to 2024). A malignant (clonal) hematologic disorder, involving hematopoietic stem cells and characterized by the presence of primitive or atypical myeloid or lymphoid cells in the bone marrow and the blood. "Different types of leukemia were also catalogued in the data gathered from patients with blood cancers, and the levels of AKT2 gene expression between different categories of leukemia were assessed." (PMID 38577021, 2024). "Specifically, AML showed higher expression levels of AKT2 compared to other leukemia types, suggesting its potential role in blood cancer pathogenesis." (PMID 38577021, 2024). "Studies have also demonstrated that AKT2 plays important roles in the carcinogenesis of leukemia." (PMID 34055775, 2021). "Considering the promotive role of AKT2 in leukemia, we hypothesized that circADD2 may sponge miR-149-5p to regulate AKT2 expression in childhood ALL." (PMID 34055775, 2021). "AKT2 inhibits leukemia cell proliferation and induces apoptosis upon experimental verification." (PMID 31373443, 2019). "In leukemia, AKT1 and AKT2 phosphorylate PHB2 at S91, regulate nuclear-mitochondria activity, and further promote cell survival." (PMID 37190120, 2023). "Several PI3K/AKT/MTOR pathway genes were identified to affect cell proliferation in the shRNA screen (e.g. PIK3CD, AKT2, AKT1, RPS6) confirming our previous data about PI3K/AKT/MTOR activation in mouse E2A-PBX1+ leukemia cells." (PMID 35794338, 2022). "AKT1 and AKT2 both interact with all TCL1 family members like TCL1, MTCP1, and TCL1b in leukemia cells and as consequence the activity of both isoforms is increased in an unspecific manner." (PMID 31752925, 2019). "ANOVA-based analysis showed a non-significant downregulation of AKT2 gene expression in myeloma compared to leukemia and lymphoma (p = 0.3742)." (PMID 38577021, 2024). "Conversely, myeloma exhibited a non-significant downregulation of AKT2 compared to leukemia and lymphoma, as well as in HL compared to NHL." (PMID 38577021, 2024). "The discovery of AKT dates back to the 1970s, when an oncogene sequence, named AKT8, was identified in murine leukemia viruses, and two homologous oncogenes of AKT8, named AKT1 and AKT2 (also known as PKKB αand PKKB β, respectively), were subsequently identified in human chromosomes." (PMID 36579349, 2022).
metastatic tumors (9 papers, 2016 to 2025). "Further, the mice injected with AKT2 KO cells showed a survival benefit relative to NT-injected mice, which is consistent with the previous results, indicating that AKT2 depletion delays the onset of metastatic disease and overall survival." (PMID 37894325, 2023). "One of the other 2 patients with increased levels of Akt3 in metastatic tumors had extremely high levels of Akt1 (7.61-fold compared to primary tumors) and Akt2 (4.68-fold compared to primary tumors)." (PMID 34591413, 2021). "Briefly, levels of Akt1 and Akt2 were increased in metastatic tumors compared to primary prostate tumors, while levels of Akt3 decreased." (PMID 34591413, 2021). "Akt1 KD mice had the fewest metastatic abdominal tumors, while both Akt2 KD and Akt3 KD mice had greater metastatic disease than control mice." (PMID 27533079, 2016). "Conversely, Akt2−/− and Akt3−/− had increased metastatic tumors, compared to controls." (PMID 27533079, 2016). "Similarly, Akt2 levels were elevated in metastatic tumors in 6 out of 8 patients." (PMID 34591413, 2021). "However, these mice were not fully protected from metastatic disease, unlike the mice inoculated with AKT2-depleted cells, suggesting AKT2 activity may be most impactful at the stage of extravasation, and its effect on tumor growth at the metastatic site was moderate." (PMID 37894325, 2023).
triple-negative breast carcinoma (9 papers, 2017 to 2025). An invasive breast carcinoma which is negative for expression of estrogen receptor (ER), progesterone receptor (PR), and human epidermal growth factor receptor 2 (HER2). "By integrating tetrahedral DNA nanostructures with carbon nanotubes, the detection of ctDNA associated with AKT2 genes in triple-negative breast cancer has been achieved, and this platform also facilitates the identification of other biomarkers." (PMID 40948789, 2025). "Similarly, Akt2 is associated with proliferation, and phosphorylation at that particular site with activation, MITF promotes cell proliferation and invasion through the yes-associated protein 1 (YAP) signaling, a molecule associated with negative prognosis in triple-negative breast cancer." (PMID 41149583, 2025).